IL13 (interleukin 13)
Diseases named in the same sentence as IL13 in open-access papers (continued):
Sharing a sentence is not in itself a finding about the gene and the disease.
tumor (continued). "Tumor cell-derived IL-33 stimulated IL-13 secretion by ILC2s that enhanced DC antigen presentation and generation of anti-tumor CTL." (PMID 32903717, 2020). "IPA analysis suggests that this is likely due to the presence of pro-M2/Th2 cytokines such as IL-4 and IL-13, in the tumor microenvironment." (PMID 32699181, 2020). "It has been well-established that in response to the Th2 cytokines interleukin-4 (IL-4) and interleukin-13 (IL-13), macrophages undergo alternative activation, gaining abilities to support tumor growth and inhibit antitumor immunity." (PMID 33178603, 2020). "Paired comparison of IL-13 in adjacent and tumor colonic tissue showed significantly higher protein concentration and IL13 transcript number in tumors but similar expression level of IL13Ra1 transcripts." (PMID 32512917, 2020). "M2 macrophages alternatively induced by Th2 cytokines (IL-4 and IL-13) act as a powerhouse for tumor angiogenesis and metastasis, by displaying an immunosuppressive phenotype and secreting abundant pro-tumor cytokines." (PMID 32512803, 2020). "We found a slight increase of tumor initiating cytokines such as TNFα, IL-17, and IL-13 in mP obese models, while a statistically significant increase in the more aggressive mT obese models." (PMID 32411709, 2020). "In ESCC, IL-13 protein concentration increased along with advancing TNM in tumor (ρ = 0.56, p = 0.016) and tumor-adjacent tissue (ρ = 0.52, p = 0.026) and tended to positively correlate with T in tumors (ρ = 0.43, p = 0.078)." (PMID 32512917, 2020). "After treatment, the overall expression of IL13-Rα2 in some patients decreased, while the tumor necrotic volume increased at the site of IL13-zetakine(+) T-cell administration." (PMID 33224149, 2020). "The IL-13Rα2 chain is also highly expressed by several tumor cells and binds with higher affinity to IL-13 than the other chain (IL-13Rα1), even when coupled to IL-4Rα." (PMID 33233582, 2020). "In CRC, systemic IL-13 significantly and positively correlated with tumor grade (ρ = 0.27, p = 0.039) and tended to correlate with tumor extension (ρ = 0.21, p = 0.080) and CRC stage (ρ = 0.21, p = 0.077)." (PMID 32512917, 2020). "Th2 cells are known to eliminate tumor cells by recruiting tumoricidal eosinophils and macrophages to the tumor microenvironment due to the secretion of IL-4 and IL-13 cytokines." (PMID 32508847, 2020). "High levels of IL-13 provoke reduced tumor immune control, which leads to unrestrained tumor growth." (PMID 33343662, 2020). "Of note, Th22 cells also showed overexpression of the IL13 gene, IL13 being a key effector cytokine in immune responses against intracellular parasites and in the modulation of tumor cell growth and apoptosis." (PMID 32174910, 2020). "In ESCC, the density of IL-13 protein in tumor stroma has been higher in early cancers and positively associated with overall and disease-free survival." (PMID 32512917, 2020). "Our results demonstrated that the level of NMU mRNA in HCC peri- and intra-tumor tissue was positively related to the levels of type-2 cytokine mRNA, including IL-4, IL-10, and IL-13." (PMID 32013887, 2020). "Involved in immune surveillance, the IL-13 tumor contributes to escape from apoptosis and strengthens its growth." (PMID 33343662, 2020). "The antitumor function of these cells is ambiguous, where most studies indicate that type II NKT-cells support tumor immunosurveillance by secreting IL13." (PMID 32582698, 2020). "IL13-PE was highly selective and potent for killing human tumor cells in vitro, in particular glioblastoma cells that expressed high levels of IL-13Rα2 chain." (PMID 32957689, 2020). "Together, they elicit a cytokinome, that includes CCL2 and IL13, enabling crosstalk between cancer cells and host macrophages that drives tumor progression." (PMID 31933479, 2020).
tumor (continued). "(b) Quantification of tumor volume of primary tumor and bioluminescence signal at 4 weeks in mice treated with ctrl ab (n = 4), anti-Ccl2 ab (n = 4) or anti-Il13 ab (n = 3) or anti-Ccl2+Il13 abs (n = 4)." (PMID 31933479, 2020). "By contrast, alternatively activated macrophages or M2 macrophages are polarized by anti-inflammatory signals, such as IL10, IL4, and IL13 and are involved in immunosuppression, tumor invasion, tumor growth, angiogenesis and metastasis." (PMID 31096567, 2019). "The milieu of cells in the tumor microenvironment produces cytokines such as IL-4, IL-10, IL-13, and M-CSF that encourage M2 or immunosuppressive phenotype differentiation." (PMID 30931508, 2019). "IL-13 is a cytokine that deviates the immune response away from a protective type 1 toward a tumor-supporting type 2 response." (PMID 31616638, 2019). "For example, macrophages exposed to IL-4, IL-10, and IL-13 differentiate into the M2 phenotype during tumor progression and secrete IL-4, IL-5, and IL-6 to enhance angiogenesis, immunosuppression, and matrix remodeling." (PMID 31192126, 2019). "IL4 and IL13 also play crucial roles in tumor biology and tumor immunology via activation of immune cells in the tumor microenvironment." (PMID 31540495, 2019). "Pro-tumor: ILC2 elevated tumor-derived PGD2 and B7H6 and activated MDSCs via IL-13 secretion to promote tumor growth." (PMID 32117199, 2019). "Like Th2, their adaptive counterparts, ILC2s produce IL-4 and IL-13, which are known to participate in the establishment of a pro-tumor microenvironment." (PMID 31024531, 2019). "It has been reported that IL4 and IL13-mediated signaling pathways play an important role in tumor biology." (PMID 31540495, 2019). "Interleukin 4 (IL-4) and Interleukin 13 (IL-13) can induce M2 macrophages, which have anti-inflammatory and tumor-promoting abilities." (PMID 31777603, 2019). "At the other extreme, M2-like macrophages, which mimic tumor-associated macrophages (TAMs) present in the tumor microenvironment (TME), can be induced by anti-inflammatory cytokines, such as IL-4 or IL-13." (PMID 31878087, 2019). "Th2 cells, on the other hand, secrete IL-4, IL-5, IL-6, IL-10, and IL-13, which induce anergy in T cells and enhance the activities of tumor-promoting macrophages." (PMID 31366131, 2019). "IL-13 can act directly on tumor epithelial cells in both an autocrine or paracrine manner to promote their survival and tumorigenesis." (PMID 32010138, 2019). "In contrast, IL-4 or IL-13 induce the M2 phenotype, which promotes tumor angiogenesis and suppresses immune responses." (PMID 31412566, 2019). "This was associated with suppression of anti-tumor CD8 T cells, reduced IFN-γ and elevated IL-13 production." (PMID 30881361, 2019). "The regulatory effect of SI-CLP is not clear yet since the cytokines induced by SI-CLP can either promote (IL-1β, IL-6, IL-13) or suppress (IL-12) tumor progression." (PMID 32038607, 2019). "This population can produce IL-13 after activation, consistent with the previous observation in the analysis of their suppressive effect in tumor immunity." (PMID 29520281, 2018). "The antiinflammatory factors, including IL-4, IL-10, and IL-13, inIL-33-treated tumor-bearing mice were also significantly increased." (PMID 29950152, 2018). "Our study was then further designed to target MPNST cancer cells using IL13 conjugated liposomes to selectively target and deliver the encapsulated chemotherapeutic agent to improve its therapeutic index and decrease tumor progression in mice bearing MPNSTs." (PMID 29304038, 2018). "Interleukin-13 (IL-13), predominantly a Th2-derived cytokine, plays an important role in fibrosis, inflammation, tissue hyperresponsiveness, and tumor development." (PMID 30643796, 2018). "IL-13, a Th2 cytokine, participates in allergic reactions, fibrosis, inflammation, and even tumor development." (PMID 30643796, 2018).
tumor (continued). "Resultsshowed that the protein levels of IL-4, IL-10, and IL-13 were significantly increased inthe serum of tumor-bearing mice, respectively (Ps < .05)." (PMID 29950152, 2018). "Once the tumor is established, tumor cells secrete cytokines IL-4, IL-10, IL-13 and lactic acid, and along with the presence of CD4+ Th2 cells, cause the polarization of TAMs toward an M2-like phenotype." (PMID 30356656, 2018). "Based on our previous studies using the GBM tumor model, it is evident that IL13 conjugated liposomal doxorubicin is effective in suppressing tumor progression and improving the survival of tumor bearing mice." (PMID 29304038, 2018). "Factors in the pancreatic cancer microenvironment, such as CSF-1, IL-4, IL-13, TGFβ and IL-10, can promote myeloid progenitor cell differentiation into monocytes and macrophages and recruit them to the tumor microenvironment." (PMID 30060755, 2018). "IL13LIPDXR is the formulation similar to Doxil, but with IL13 cytokine attached on the surface PEG groups for improved tumor-specific targeting." (PMID 29304038, 2018). "Thereafter, it was shown that IL-13 induced TGF-β-secreting myeloid-derived suppressor cells (MDSCs) in vivo that inhibited tumor-specific T cells." (PMID 29535734, 2018). "Yet, tumour cells and the irradiated tumour microenvironment also produce M2 activators (IL-4, IL-10, IL-13, TGF-β, and PGE2)." (PMID 30178305, 2018). "In DIPG tissues, transcript-level analysis found significant expression of IL-4, IL-13, and IL-13Rα1/2, with strong differential expression of IL-13Rα1/2 in tumor versus normal brain." (PMID 29621254, 2018). "IL-13 has been shown to activate tumor-promoting MDSCs and their production of anti-inflammatory transforming growth factor-beta (TGF-β)." (PMID 30631327, 2018). "In the TME, the presence of CAFs and their secretion of CCL2, CCL5, and CCL17 as well as the polarizing cytokines IL-1, IL-6, IL-13, and IL-26 can favor a tumor promoting TH2 and TH17 immune response, as the expense of tumor protective TH1 response." (PMID 29545811, 2018). "A previous study has revealed that distinct cellular sources of IL-13, as well as precise targets of IL-13 that contribute to tumor progression, focus on both cells of hematopoietic lineage as well as epithelial and stromal cells." (PMID 30643796, 2018). "It is possible that IL-13 secreted by other cells can migrate to tumor bed and in turn activate AP-1 factors." (PMID 30572904, 2018). "To confirm the upregulation of AP-1 transcription factors in IL-13Rα2 positive GBM tumor cell lines at molecular level, we performed RT-qPCR analysis to quantitate mRNA expression of all five AP-1 transcription factors in IL-13 treated GBM cell lines." (PMID 30572904, 2018). "A study has revealed that IL-13 along with Th2 cytokines such as IL-10 and IL-4 assist in the immunological tumor escape and interfere with the induction of an antitumor response." (PMID 30643796, 2018). "Our subsequent in vivo investigation in the STS26T MPNST sciatic nerve tumor model indicated that IL13 conjugated liposomal doxorubicin (IL13LIPDXR) was more effective in inhibiting tumor progression compared to unconjugated liposomal doxorubicin (LIPDXR)." (PMID 29304038, 2018). "In the tumor microenvironment, various factors such as IL-13, PGE2, macrophage colony-stimulating factor (M-CSF), vascular endothelial growth factor, and lactic acid promote M2 macrophages development." (PMID 29491374, 2018). "In general, macrophages that infiltrate tumor tissues are driven by tumor-and T cell-derived cytokines to acquire a polarized M2 phenotype characterized by production of IL-4, IL-13, IL-10, and glucocorticoid hormones." (PMID 30042333, 2018). "Tumor cells produce cytokines responsible for the recruitment and polarization of macrophages to M2 profile such as IL-4, IL-10, IL-13, and TGF-β, as well as chemokines such as CCL2 (MCP-1), CCL3, and CCL14." (PMID 28970834, 2017).
tumor (continued). "Treatment of mice expressing oncogenic KRAS with neutralizing antibody for IL-13 reduces tumor formation." (PMID 29156578, 2017). "For example, in an earlier CED trial using IL13-based cytotoxin, it was later estimated that only about 20% of the tumor volume was covered by the therapy, which greatly contributed to only showing modest benefits and not meeting the trial endpoints." (PMID 28562337, 2017). "Cytokines, like TNF, IL-1β, IL-4, IL-13, and TGF-β, secreted by medullary cells, can also lead to the mutation of cancer related genes, and thus, the promotion of tumor formation." (PMID 29212288, 2017). "IL-13 is a key regulator of type 2 helper T cells (Th2) that suppress anti-tumor immune surveillance, thus facilitating cancer invasion and metastasis." (PMID 28178674, 2017). "A major attribute of type II NKT-mediated suppression of tumor immunity is elevated production of IL-13 and IL-4 cytokines capable of skewing the cytokine response predominantly toward tumor-promoting Th2 type." (PMID 29018445, 2017). "Th22 cells contribute to the increased abundance of IL-22+/IL-13+ T cells, thereby leading to poor prognosis in MM based on the effects of pDCs in the tumor microenvironment." (PMID 29085361, 2017). "Th2 cells generate IL-4 and IL-13 to promote tumor growth by stimulating tumor cell proliferation or promoting tumor cell resistance to apoptosis." (PMID 27935860, 2017). "In some cancers, including breast 72, gastric 73 and pancreatic cancer 74, 75, Th2 cells and associated cytokines [IL‐4, IL‐13, Thymic stromal lymphopoietin (TSLP)] contribute to tumour progression." (PMID 28032353, 2017). "In contrast, some studies provide the finding that Th2-derived cytokines (IL-4, IL-5, IL-10, and IL13) show anti-tumor activities in vivo that are as strong as the anti-tumor activities of Th1 cytokines." (PMID 29299026, 2017). "In fact, even in a Th2‐M2 tumour microenvironment macrophages stimulated by IL‐4 and IL‐13 were able to inhibit proliferation of B16‐F1 melanoma cells." (PMID 28032353, 2017). "Here the authors show that, in acute promyelocytic leukaemia, tumour-activated ILC2s secrete IL-13 to induce myeloid-derived suppressor cells and support tumour growth." (PMID 28928446, 2017). "Of the two major macrophage phenotypes (M1 and M2), the M2 phenotype of TAMs in the tumor region are basically regulated by a subset of tumor-secreted factors, such as M-CSF, IL-4, IL-13 and IL-10." (PMID 28032600, 2017). "In the tumor site of action, TAMs produce cytokines such as IL-10, IL-4, and IL-13 that will act to repair tissues and attract other auxiliary cells that can activate TAM and hence, promoting tumor growth." (PMID 28970834, 2017). "Natural killer T (NKT) cells are a subpopulation of T lymphocytes, which are considered tumor cell killers; they produce antitumor molecules, such as Fas ligand (FasL), IL-4, IFN-γ, IL-13, perforin, and granzyme, that also promote lysis of tumor cells." (PMID 27294132, 2016). "While IL-13 is protective, IL-4 clearly promotes tumour growth in this model and is mainly produced by the inflammatory infiltrate." (PMID 27357235, 2016). "In cancer, soluble cytokines such as granulocyte macrophage colony stimulating factor (GM-CSF), granulocyte colony stimulating factor (G-CSF), interleukin-13 (IL-13), interleukin-4 and interferon-γ are secreted into the tumor microenvironment." (PMID 27507680, 2016). "Tumor derived cytokines such as IL-4, IL-10, IL-13, TGFβ and prostaglandin E2 can drive the production of M2 macrophages while IL-12 is produced by M1 macrophages." (PMID 26654940, 2016). "The expansion and activation of MDSCs is regulated by several factors (e.g. IL-4, IL-13, IL-1α, INFγ and GM-CSF) that are released by activated macrophages and T cells, tumor cells, tumor stromal cells, and by pathogen-infected cells." (PMID 27191744, 2016).
tumor (continued). "We further found that distribution densities of CD68 and IL-13 in tumor stroma area were positively correlated with ESCC patients’ overall survival after operation." (PMID 26771842, 2016). "Distribution features of CD1A, CD123, CD57, CD66b, CD68 and IL-13 were detected in 20 ESCC patients’ tumor tissues with IHC staining." (PMID 26771842, 2016). "Mechanistic studies showed that PGN first induced an IL13 response in the irradiated intestine, but was decreased in tumor cell models screened by Th1/Th2 FlowCytomix assay and validated by the application of IL13 and anti-IL13 neutralizing antibodies." (PMID 27708223, 2016). "IL-33 stimulates ILC2s to secrete large amounts of IL-13, which has been shown to activate tumor-promoting MDSCs and their production of anti-inflammatory transforming growth factor-β (TGF-β)." (PMID 28536374, 2016). "Apart from the differences in the expression of IL13 in the small intestine and tumor, IL13 also has two kinds of receptor." (PMID 27708223, 2016). "Since AD is associated with allergen sensitization, elevated serum IgE and increased expression of Type 2 cytokines (IL-4, IL5, and IL-13) in both unaffected skin and skin lesions of AD, candidate gene studies for AD have also focused on the Th2 pathway." (PMID 27777593, 2016). "So we further combined TNM stage and densities of CD68 and IL-13 in tumor stroma to construct a united model for ESCC prognosis prediction, which proved to can provide more accuracy prognosis prediction for ESCC patients after operation." (PMID 26771842, 2016). "One of the reported mechanisms for tumor escape is that recruited immune cells express cytokines such as IL-13 and IL-4 to generate a tumor-favoring microenvironment." (PMID 27081854, 2016). "The M1 population is thought to be beneficial in a tumor environment (including solid tumors and circulating tumor cells) but this environment is overwhelmed by anti-inflammatory signals, and type-II cytokines (e.g. IL-4, IL-10 and IL-13) tend to dominate." (PMID 27564103, 2016). "So the correlation between density of CD68 as well as IL-13 in tumor stroma and patients’ survival time was further confirmed by a TMA containing 194 ESCC tumor samples from the same center (training set)." (PMID 26771842, 2016). "IFN-γ-deficient mice failed to respond similarly, and we found elevated levels of IFN-γ, IL-10, and IL-13 (among 15 examined) present in tumor lysate supernatants from wild-type mice treated with both antibodies than with either antibody alone." (PMID 27610613, 2016). "Because production of IL-4 and IL-13 was markedly upregulated in sST2 low-expressing tumours, we assumed that the proportion of the M2a subset was increased in these tumours." (PMID 27882929, 2016). "In support of a role for IL-13 in promoting antitumor activity, P815 cells expressing IL-13 grew slower than parental tumor cells." (PMID 27610613, 2016). "IL13, one of many immune inhibitory cytokines generated by Th2 lymphocytes, is involved in tumor development by inhibiting immune surveillance functions of natural killer cells, CD4 (+) Th1 cells and CD8 (+) cytotoxic T lymphocytes." (PMID 27167201, 2016). "In vitro experiments indicated that IL-13 promotes CTCL tumor cell proliferation via auto-secretion and leads to a worse prognosis of CTCL patients." (PMID 27589565, 2016). "We also found that ESCC patient in advanced TNM stage had relatively low tumor stroma IL-13 density and low union score." (PMID 26771842, 2016). "In response to polarization signals, such as IL-4, IL-13, transforming growth factor-β, and matrix metalloproteinase-9, monocytes in the tumor polarize into M2 macrophages." (PMID 27129159, 2016). "By contrast, type II NKT cells were found to suppress anti-tumor immunity in several mouse models by producing IL-13." (PMID 26217516, 2015).